MMP2 (matrix metallopeptidase 2)
Diseases named in the same sentence as MMP2 in open-access papers (continued):
Sharing a sentence is not in itself a finding about the gene and the disease.
diabetes (continued). "Diabetics with CAD showed an increased plasma concentration of MMP-2 as well as an increased MMP-2 in supernatants after platelets aggregation in comparison to CAD patients without diabetes." (PMID 28770228, 2017). "The increased MMP-1, MMP-2, and MMP-9 activities and expression induced by high glucose exposure can elevate matrix degradation thereby accelerating atherogenesis and potentially decreasing plaque stability in diabetes." (PMID 27781209, 2016). "Overexpression of MMP-2 and MMP-9 in diabetic atherosclerotic plaques may increase their vulnerability which, in turn, increases the risk of ischemic cardiovascular events." (PMID 27490532, 2016). "Diabetes can also induce expression of TNF-α, MMP-2, and MMP-9 in the retina which may enhance apoptosis in the tissue and contribute to the pathogenesis of diabetic retinopathy." (PMID 25821481, 2015). "Moreover, DHI inhibited CAS-3, MMP-2 and MMP-9 expression and formation of acellular capillaries in retinas that can prevent diabetes-induced apoptosis and protect retinas against diabetes-induced damage." (PMID 26061387, 2015). "Moreover, we observed that the induction of retinal CAS-3, TNF-α, MMP-2, and MMP-9 expressions by diabetes was inhibited by NXT treatment, suggesting an antiapoptotic and anti-inflammatory effects of NXT." (PMID 25821481, 2015). "MMP-2 mRNA and protein levels were significantly higher in the diabetes group than in negative controls (P < 0.001); meanwhile, gene and protein TIMP-2 expression was also higher in diabetes group." (PMID 26526881, 2015). "Note that the levels/activity of MMP-2 in the gingiva is not affected either by diabetes or by treatment with CMC 2.5." (PMID 24453415, 2013). "Then, the aim of this study was to investigate the possible microbiological changes and the spatial distribution and the number of immunostained cells to RAGE, TNF-alpha, IL-1beta, IL-6, RANKL and MMP-2, and MMP-9, in periodontal tissue after diabetes induction." (PMID 22611374, 2012). "However, some studies report increased MMP activity, particularly MMP-1, MMP-2, and MMP-9, with higher blood glucose levels, which could counteract any protective effect of diabetes against AD." (PMID 39105077, 2024). "At baseline, MMP‐2 levels and activity were significantly higher in people with type 1 diabetes with or without complications compared with the control group of people without diabetes (P < .001 for both)." (PMID 33855203, 2021). "Furthermore, Parkar, Bhatt, and Addepalli hypothesized that nobiletin, due to its metalloproteinase (MMP)-2- and MMP-9-inhibitory and antioxidant potential, could ameliorate the cardiovascular dysfunction in diabetes." (PMID 32977511, 2020). "Moreover, MMP2 has been shown to be expressed in pancreatic islets of Zucker diabetic fatty (ZDF) rats, and the expression and activity of MMP2 were increased along with the onset of islet dysfunction and diabetes." (PMID 25333278, 2014). "Consequently, a refined selection comprising seven genes (MMP2, MMP9, IL17A, IL10, FGF2, IL6 and VEGFA) and eleven pharmacological agents has emerged, exhibiting promise in delivering therapeutic effects aimed at mitigating the occurrence of OP in individuals afflicted with diabetes." (PMID 38250601, 2024). "In addition, MMP-2 has been found to demonstrate increased immunoreactivity in LECs of patients with cataracts and diabetes mellitus; MMP-2 may hence play role in the pathogenesis of cataracts in subjects with diabetes mellitus." (PMID 35457074, 2022). "Additionally, in connection to other cardiac parameters, nobiletin reduced MMP-2 and MMP-9 enzymatic activities in the heart, improved the cardiac hypertrophy index, attenuated the deterioration in the morphology of cardiomyocytes, and reduced diabetes-induced myocardial fibrosis in the rats." (PMID 32977511, 2020).
diabetes (continued). "The imbalance of MMP2/TIMP2 and MMP9/TIMP1 contributes to the non-injured skin disorder of collagen deposition in diabetes, suggesting a possibility for early treatment of diabetes skin complications." (PMID 34777244, 2021). "Among the MMPs examined, MMP-1, MMP-2, MMP-3, and MMP-7 were detected in all vitreous samples from patients with PDR and control patients without diabetes." (PMID 24392031, 2013). "This part of the network is in agreement with other previously reported data showing that MMP2 is dysregulated in the arterial wall in diabetes and seems to indicate that matrix remodeling may be an important feature of the non-atherosclerotic arterial disease seen in diabetes." (PMID 22340758, 2012). "Further adjustment for height, body mass index, systolic blood pressure, antihypertension therapy, diabetes status, current smoker, current alcohol use, and total and HDL cholesterol did not appreciably change point estimates for MMP-2, TIMP-2, VCAM-1, or SLPI." (PMID 34521347, 2021). "Also, increased retinal levels of MMP-2 were found in rats and mice with STZ-induced diabetes compared to non-diabetic controls." (PMID 25848912, 2015). "However, the effects of both diabetes and CMC 2.5 treatment on plasma MMP-2 were not statistically significant, although the pattern of change for this 72 kDa gelatinase paralleled the changes seen for the other MMPs." (PMID 24453415, 2013).
Hypertension (116 papers, 2008 to 2026). The presence of chronic increased pressure in the systemic arterial system. "The HSF diet caused metabolic disturbances, including hypertension, increased adiposity, and insulin resistance, accompanied by myocardial remodeling, inflammation, and elevated MMP-2 activity." (PMID 41588666, 2026). "Changes in MMP-2 and -9 underlie arterial remodeling, determining pathological disorders that include hypertension." (PMID 39452936, 2024). "Nitrite effectively impedes the activation of MMP2 via XO-mediated antioxidant mechanisms and reverses vascular structural alterations associated with hypertension." (PMID 39070552, 2024). "Quercetin, a flavonoid, suppresses the MMP-2 activity, thereby mitigating hypertrophic vascular remodeling associated with hypertension." (PMID 38766523, 2024). "We previously reported a significant increase in leukocyte MMP-2 expression in children/adolescents with essential hypertension, and up-regulation of MMP-2 expression has been found to be associated with the adipose tissue development." (PMID 38541059, 2024). "In animal models of hypertension, the association between elevated MMP-2 activity and altered conductance and resistance of arteries has been demonstrated." (PMID 36835040, 2023). "Only MMP-2 rs7201 A > C and rs14070 C > T were positively associated with increased urinary Cd concentration and hypertension risk in Chinese population." (PMID 36430020, 2022). "Recently, it has been observed that single nucleotide polymorphisms (SNPs) in the MMP-2 gene can modify the association between Cd exposure and hypertension in a Chinese population." (PMID 36430020, 2022). "The antioxidant tempol, which previously was shown to decrease vascular MMP-2 activity in hypertension, prevented calponin-1 loss in 2K-1C hypertensive rats, possibly by decreasing MMP-2 S-glutathionylation." (PMID 33923477, 2021). "Tumor necrosis factor-α (TNF-α) is another cytokine implicated in the vascular remodeling of hypertension, as it is essential for Ang-II-induced MMP-2 expression." (PMID 33923477, 2021). "While most studies have implicated MMP-2 as a major cause of vascular dysfunction in hypertension, MMP-9 is apparently also involved." (PMID 33923477, 2021). "Apart from Mmp11 which is a matrix metalloproteinases as Mmp2 we selected Ptgs1, Ptgs2 and Olr1 due to their possible relation to the vascular changes associated with hypertension." (PMID 28880918, 2017). "Drugs used in the treatment of hypertension, such as verapamil, carvedilol and trimetazidine, have shown positive effects on cardiac function and remodeling associated with decreased activity and expression of MMP-2." (PMID 35893744, 2022). "Moreover, high total cfDNA was associated with adverse clinical outcomes (high blood pressure, low platelet count, preterm delivery, fetal growth restriction) and high prohypertensive factors (sFLT-1, sEndoglin, MMP-2)." (PMID 33429954, 2021). "In the VdH cohort, MMP-2 levels were associated with age (0.95; 95% CI 0.27 to 1.63, p = 0.007), mRS 90 days (3.8; 95% CI 0.48 to7.07, p = 0.025), hypertension and 90-days mortality (OR = 1.032, 95% CI 1.002 to 1.064, p = 0.039 and OR = 1.025, 95% CI 1.003 to 1.048, p = 0.027, respectively)." (PMID 32587306, 2020). "MMP-2 is constitutively expressed in vascular SMCs of normal arteries and was found to be linked to a number of pathological conditions, including atherosclerotic arteries and hypertension." (PMID 26571308, 2015). "Importantly, hypertensive rats exhibited inherently higher basal levels of remodeling activity and MMP-2 expression compared to normotensive controls, and showed a more pronounced response to chronic stress, suggesting hypertension may predispose bone tissue to increased metabolic vulnerability." (PMID 41799065, 2026). "In hypertension, MMP-2 is upregulated, leading to increased ECM degradation and vascular remodeling." (PMID 40492135, 2025).
Hypertension (continued). "MMP-2 has been shown to activate the β-adrenergic receptor, leading to an increase in catecholamine-mediated vasoconstriction and hypertension." (PMID 40492135, 2025). "For example, pulmonary macrophage–derived LGMN promotes hypertension by activating MMP-2/TGF-β1 signaling in pulmonary artery smooth muscle cells." (PMID 40131864, 2025). "Quercetin, a pivotal flavonoid with pronounced antioxidant properties, attenuates hypertension-induced aortic remodeling, oxidative stress, and MMP2 activity." (PMID 39070552, 2024). "MMP-2 is expressed constitutively on the cell surface, and it is involved in hypertension induced by maladaptive vascular remodeling by degrading extra- and intra-cellular proteins." (PMID 39452936, 2024). "Hypoxia can stimulate MMP-2 expression, and MMP-2 is capable of cleaving big endothelin (ET)-1 and induce hypertension through the generation of ET-1, a potent vasoconstrictor." (PMID 38074158, 2023). "A study with hypertension and cardiac hypertrophy found that increased cardiac MMP2 contributes to the transition of concentric to eccentric LV hypertrophy and cardiac dysfunction." (PMID 36818345, 2023). "In the treatment of hypertension, quercetin can reduce hypertension induced aortic remodeling, oxidative stress, and MMP-2 activity." (PMID 38054093, 2023). "MMP-2 is related to hypertension because it can degrade a series of myofilament proteins correlated with contractility, decreasing myofilament sensitivity to Ca2+, and triggering contractile dysfunction." (PMID 37372128, 2023). "Suggested mechanisms of promoting arterial hypertension by MMP-2 excessive activity involve both the degradation of vasoconstrictors with the formation of more potent substances constricting the vessels and the cleavage of vasodilators." (PMID 36835040, 2023). "Quercetin improved hypertension-induced vascular remodeling in hypertensive rats by reducing aortic oxidative stress and MMP2 activity." (PMID 36611616, 2022). "Vasoactive factors are released by increasing MMP2 and MMP9, which further increases the risk of hypertension during late gestation." (PMID 36910123, 2022). "Along with inflammation, cardiovascular remodeling during hypertension is accompanied by increased MMP2 activity." (PMID 35133978, 2022). "A correlation study in children with obesity hypertension showed the induction of plasma levels of MMP-2 and MMP-9 in patients with obese." (PMID 36034923, 2022). "MMPs were found in higher concentrations in atherosclerotic plaques, and patients with hypertension, myocardial infarction, and unstable angina had higher levels of circulating MMP2 and MMP9 than healthy people." (PMID 35050217, 2021). "In fact, the antagonist of β-adrenergic receptors, nebivolol, attenuates hypertension-induced vascular remodeling and increases vascular MMP-2 activity." (PMID 33923477, 2021). "It is also observed that in the patients having LV hypertrophy and with a history of hypertension, plasma levels of MMP-2 were significantly enhanced as compared to control subjects." (PMID 33747350, 2021). "To further clarify the therapeutic mechanisms of TTR on pregnant hypertension, we investigated the MMP‐2 and MMP‐9 expressions in placental tissues." (PMID 32533762, 2020). "Elevated levels and activities of MMP-2 have been observed in vascular remodelling due to hypertension." (PMID 33023122, 2020). "After stabilization of hypertension, i.e., in 20-week-old animals, plasma MMP-2 activity is the same in WKY rats and in SHR." (PMID 33023122, 2020). "In 7-week-old animals, i.e., during the development of hypertension, we were able to observe higher MMP-2 activation in SHR when compared with WKY rats." (PMID 33023122, 2020). "Regarding MMP-2, several studies support the association of MMP-2 with hypertension and mortality in diabetic patients and in patients with heart failure." (PMID 32587306, 2020).
Hypertension (continued). "There is a parallel with a study describing humans, in which stabilized arterial hypertension was accompanied by the decrease in plasma MMP-2 activity in comparison with normotensive controls." (PMID 33023122, 2020). "Hypertension also contributes to the activation of MMP-2 and vascular remodeling through the mechanical stress induction." (PMID 31781384, 2019). "The increased production of ROS in vessels contributes to the activation of MMP-2, thereby inducing the development of hypertension and other chronic cardiovascular alterations." (PMID 31781384, 2019). "Regarding SHRs, it should be noted that the levels of TGF-β1 were lower, SMAD2/3 were similar, and MMP-2 along with collagen deposition were higher than those observed in WKRs; this most likely reflects the adaptation of 12-month-old SHRs to hypertension." (PMID 31374823, 2019). "Previous studies have reported that apelin promotes collagen deposition and increases the expression of MMP-2 or MMP-9 in overnourished mice or rats with hypertension-induced left ventricular hypertrophy." (PMID 31829402, 2019). "It most likely follows that the expression of MMP-2 is induced at the beginning of hypertension process; therefore, its increased levels mainly reflect early changes in ECM, provided that there are no other vascular complications." (PMID 31781384, 2019). "Clinical reports indicated a decreased MMP-2 protein expression in plasma from patients with hypertension." (PMID 30133537, 2018). "Another study showed similar results, demonstrating the depression of MMP-2 activity in plasma concentrations of patients with essential hypertension." (PMID 30133537, 2018). "Another study found that arterial remodeling, observed in an animal model of Hhcy-induced arterial hypertension, was in part due to increased MMP-2 and MMP-9 activation." (PMID 28133545, 2017). "We also exclude that other factors such as arterial hypertension, history of myocardial infarction, and hypercholesterolemia had an influence on MMP-2 level in DM patients." (PMID 28770228, 2017). "The increased gene expression in hypertensive cerebral arteries is supported by an increased expression and activation of Mmp2 by mechanical stretch such as hypertension in human aortic SMCs." (PMID 28880918, 2017). "It was therefore suggested, that both Timp1 and Mmp2 were potential plasma biomarkers of cardiovascular remodeling in response to hypertension." (PMID 28880918, 2017). "MMP-9, similar to MMP-2 is induced at the early stages of hypertension, and this is probably favorable to alleviate the initial vascular tensile stress." (PMID 27490532, 2016). "In patients with hypertension, it has been found that the plasma levels and activity of MMP-2 and MMP-9 can be increased, decreased, or unchanged." (PMID 27490532, 2016). "In experimental models of hypertension and vascular diseases, MMP-2 and -9 expressions and/or activities were modulated by proinflammatory and oxidative stress stimuli." (PMID 24743169, 2014). "Clinical and experimental studies have reported increased expression and activity of MMPs, particularly MMP-2 in the vascular tissues in animal hypertension models." (PMID 24921930, 2014). "In the same model of hypertension, the inhibition of NF κB resulted in the reduction of the transcription rate of MMP-2, MMP-9 and ROS production." (PMID 25535075, 2014). "Collectively, these data support the idea that the proteasome is critically involved in controlling the balance of TIMP1/TIMP2 expression and MMP2 activity which in turn modulates aortic extracellular matrix turnover in hypertension." (PMID 24205262, 2013). "Immunodetection of renal cortical tissue extracted protein revealed that in Ang II induced hypertension, the expression of MMP-2 and -9 were upregulated whereas, their inhibitory molecules TIMP-2 and -4 were diminished." (PMID 24386282, 2013).